ATG5 (autophagy related 5)
Diseases named in the same sentence as ATG5 in open-access papers (continued):
Sharing a sentence is not in itself a finding about the gene and the disease.
asthma (40 papers, 2012 to 2026). "For example, one study shows that ATG5 skews the Th2/Th1 balance toward increased levels of Th2 cells, which causes airway inflammatory reactions and accelerates the development of asthma." (PMID 37644509, 2023). "Studies has demonstrated that genetic polymorphisms of the ATG5 in patients with asthma are related to airway remodeling and impairment." (PMID 37181813, 2023). "Our study found that ATG5 was positively related to the exacerbation risk and severity in adult asthma patients." (PMID 37644509, 2023). "It was also noteworthy that ATG5 was positively linked with exacerbation severity in asthma patients (P = 0.005)." (PMID 37644509, 2023). "ATG5-deficient mice exacerbate neutrophil airway inflammation and cause exacerbation of steroid-resistant asthma involving IL-17A." (PMID 37090692, 2023). "Human asthma-associated polymorphisms in Atg5 are correlated with reduced lung function and with promotion of airway remodeling in patients with severe asthma, as well as in childhood asthma." (PMID 37627282, 2023). "Serum ATG5 is related to increased Th2/Th1 ratio, inflammation, exacerbation risk and severity in adult asthma patients, which serves as a candidate marker for the management of asthma." (PMID 37644509, 2023). "In candidate gene association studies, polymorphisms of Atg5 have been associated with asthma, including childhood asthma." (PMID 35608088, 2022). "In previous GWAS, ATG5 was found to be associated with allergic diseases, including asthma, and with several other chronic diseases such as systemic lupus erythematous, rheumatoid arthritis, and multiple myeloma." (PMID 35624665, 2022). "Increased expression of ATG5 protein is found in airway epithelial cells in severe asthma and associated with subepithelial fibrosis and increased expression of collagen-1." (PMID 35608088, 2022). "Two ATG5 SNPs, rs12201458 and rs510432, were significantly associated with asthma, the latter being functionally relevant by enhancing promotor activity." (PMID 34019141, 2021). "Recent studies reveal the high correlation of the nucleotide polymorphism of ATG5/7 and the development of asthma in pediatrics and adults." (PMID 33542675, 2021). "Several studies have reported that ATG5 gene polymorphisms are associated with childhood asthma, and that the expression of the ATG5 gene is increased during acute asthma exacerbations in nasal epithelial cells." (PMID 30154478, 2018). "Autophagy, a cellular degradation process, has been shown to be dysregulated in various fibrotic diseases, and genetic association studies in independent human populations have identified autophagy-related 5 (ATG5) to be associated with asthma pathogenesis." (PMID 28424691, 2017). "Multiple lines of evidence have demonstrated that several ATG5 polymorphisms influence patient predisposition to various inflammatory diseases, including asthma, SLE and Parkinson’s disease, by altering ATG5 expression levels and autophagy activity." (PMID 28839236, 2017). "Protein expression of ATG5 in the airways was measured and associations were assessed for asthma per se, severity, and lung function." (PMID 28424691, 2017). "A growing number of studies indicated that several ATG5 promoter polymorphisms, including rs510432 and rs506027, were involved in various inflammatory diseases such as asthma, Behcet’s disease and systemic lupus erythematosus." (PMID 28839236, 2017). "Genetic variation in ATG5 has previously been linked to systemic lupus erythematosus (same SNP), asthma and neurodegenerative disease, indicating the important role of ATG5 in human health and disease." (PMID 24739953, 2014). "To detect additional ATG5 SNP associations with asthma in the GCPCR cohort, we imputed 112 SNPs located on chromosome 6 between 106734603 and 106885077 base pairs where ATG5 is located." (PMID 22536318, 2012). "In three independent cohorts, additional variants in ATG5 in the same LD block were associated with asthma (p<0.05)." (PMID 22536318, 2012).
asthma (continued). "Our data provide strong evidence for association of a functional promotor SNP in ATG5 with childhood asthma." (PMID 22536318, 2012). "We identified 2 SNPs in ATG5 associated with asthma, including one in the putative promotor, which we demonstrate to be functionally relevant." (PMID 22536318, 2012). "The increased promotor activity of the allele associated with increased risk of asthma (G) is consistent with our gene expression studies showing increased gene expression of ATG5 in asthmatics." (PMID 22536318, 2012). "We identified two variants in the ATG5 gene that are associated with asthma using a genetic association study and uncovered additional novel associations using genotypes inferred through imputation." (PMID 22536318, 2012). "We next examined associations of ATG5 SNPs with asthma in three additional independent cohorts: CAMP, CARE and CINCY using available genome-wide SNP data." (PMID 22536318, 2012). "We demonstrated that ATG5 single nucleotide polymorphisms rs12201458 and rs510432 were associated with asthma (p = 0.00085 and 0.0025, respectively)." (PMID 22536318, 2012). "Genetic variants in ATG5, including a functional promotor variant, are associated with childhood asthma." (PMID 22536318, 2012). "We have demonstrated that ATG5 variants are associated with childhood asthma, including a variant that confers enhanced promotor activity and that Atg5 expression is dysregulated in children with asthma." (PMID 22536318, 2012). "Future studies are required to determine if ATG5 has a causal role in asthma or if these differences are due to inflammation and related cell death." (PMID 22536318, 2012). "Polymorphisms in the autophagy-related gene Atg5 are strongly associated with asthma." (PMID 39544928, 2024). "ATG5 single nucleotide polymorphism is closely associated with the development of childhood asthma." (PMID 37090692, 2023). "Therefore, this study aimed to evaluate the ATG5 level and its correlation with the Th2/Th1 ratio, inflammatory cytokines, exacerbation risk and severity in adult asthma patients." (PMID 37644509, 2023). "Likewise, enhanced eosinophilic inflammation and airway hyperreactivity are also observed in ATG5-deficient obese mice compared to wild type obese mice, suggesting that autophagy mitigates the exacerbation of eosinophilic inflammation in obese asthma." (PMID 37181813, 2023). "Therefore, ATG5 was positively associated with the exacerbation risk and severity in adult asthma patients." (PMID 37644509, 2023). "Notably, ATG5 was positively linked with exacerbation severity in adult asthma patients (P = 0.005)." (PMID 37644509, 2023). "Furthermore, genetic polymorphisms in Atg5 and Atg7 genes were linked to airway remodeling and impairment in respiratory system mechanics in individuals with pediatric and adult asthma." (PMID 37627282, 2023). "Moreover, genetic mutations in autophagy genes have been associated with asthma; for example, polymorphisms in ATG5 correlate with airway remodeling and loss of lung function in asthma." (PMID 35057008, 2022). "Genomics studies have identified autophagy-related genes; the rs12212740 gene locus of ATG5 is strongly related to the development of asthma, in which the G allele is considered a risk factor for asthma and positively correlated with a decrease in forced expiratory volume in 1 s." (PMID 36330226, 2022). "Interestingly, correlations have also been drawn between high genetic polymorphisms of Atg5 in both adult and childhood asthma patients." (PMID 32733448, 2020). "In addition to asthma per se, ATG5 polymorphism was associated with lung function in asthmatic individuals." (PMID 28424691, 2017). "Furthermore, polymorphisms in the essential autophagy gene Atg5 have recently been implicated in asthma susceptibility." (PMID 26910010, 2016). "In each cohort, ATG5 SNPs were nominally associated with asthma (p<0.05)." (PMID 22536318, 2012). "Several other ATG5 SNPs were found to be associated with childhood asthma." (PMID 22536318, 2012).
asthma (continued). "Two variants in ATG5 were significantly associated with asthma in the GCPCR." (PMID 22536318, 2012). "Among asthma cases, we next examined whether ATG5 or ATG7 SNPs were associated with pulmonary function tests, including FEV1 (% predicted) and FEV1/FVC (% predicted)." (PMID 22536318, 2012). "The findings of positive association between the gene expression of various collagens (i.e., COL5A1 and less significantly COL1A1) and ATG5 supported the speculation that enhanced autophagy is associated with asthma pathogenesis and in particular collagen deposition." (PMID 28424691, 2017). "The minor allele (A) of ATG5 rs12201458 was associated with a decreased risk of asthma (p = 0.00085; OR = 0.52, 95% CI, 0.36–0.77), while the minor allele (G) of ATG5 rs510432 was associated with increased asthma risk (p = 0.0025; OR = 1.47, 95% CI, 1.14–1.88)." (PMID 22536318, 2012). "A study conducted in Atg5 knockout mice demonstrated reduced inflammation and decreased airway hyperresponsiveness in an ovalbumin-induced asthma model." (PMID 41049431, 2025). "On the other hand, genetic polymorphisms in ATG5 (−769T>C, −335G>A, and 8830 C>T) and ATG7 (−100A>G and 25108 G>C), were correlate with neutrophilic airway inflammation in adult asthma." (PMID 39417697, 2024). "Future research should enroll disease controls to further comprehensively verify the potential of ATG5 as a marker in adult asthma patients." (PMID 37644509, 2023). "MicroRNA such as microRNA-30a target ATG5 and attenuate airway fibrosis in asthma by inhibiting autophagy." (PMID 36803515, 2023). "It is reported that ATG5 also participates in airway inflammation in asthma patients to a certain extent." (PMID 37644509, 2023). "ATG5 was increased in adult asthma patients at exacerbation compared to adult asthma patients at remission [median (IQR): 53.6 (37.6–90.0) vs. 35.6 (28.2–51.5) ng/mL] (P < 0.001)." (PMID 37644509, 2023). "Autophagy-related proteins ATG5 and Becilin1 were increased in the OVA-induced asthma mouse model in the vitamin D-deficient group, compared with the vitamin D-sufficient group." (PMID 37090692, 2023). "ATG5 was elevated in adult asthma patients compared with HCs [median (IQR): 44.2 (31.7–77.8) vs. 23.2 (16.7–39.2) ng/mL] (P < 0.001)." (PMID 37644509, 2023). "Increased levels of Atg5 protein expression were found in airway epithelial cells from patients with severe asthma and correlated well with subepithelial fibrosis and increased levels of collagen-1 expression." (PMID 37627282, 2023). "ATG5, as one of the essential proteins regulating autophagy, is considered to overexpress and mediate immune responses in asthma." (PMID 37644509, 2023). "Meanwhile, ATG5 showed a certain value to discriminate adult asthma patients at exacerbation from adult asthma patients at remission with AUC of 0.732 (95% CI: 0.663–0.801)." (PMID 37644509, 2023). "ATG5 was increased in asthma patients compared with HCs [median (interquartile range): 44.2 (31.7–77.8) vs. 23.2 (16.7–39.2) ng/mL] (P < 0.001)." (PMID 37644509, 2023). "Autophagy is dysregulated in asthma, and ATG5 has attracted wide attentions as a representative gene of autophagy." (PMID 37919667, 2023). "The increased level of ATG5 was reported to be related to collagen COL5A1 mRNA expression in airways of patients with refractory asthma." (PMID 35820707, 2022). "In human studies, Atg5 expression was upregulated in the nasal epithelium of asthma patients with acute exacerbation compared with stable asthma patients." (PMID 35392563, 2022). "The expression of Beclin 1 and ATG5 in airway smooth muscle cells is increased in patients with asthma." (PMID 36330226, 2022). "Patients with asthma had higher levels of autophagy-related protein including Beclin 1 and Atg5 in lung tissue than healthy participants." (PMID 35392563, 2022). "Another study investigated the potential association of SNPs in ATG genes (ULK1, SQSTM1, MAP1LC3B, BECN1, and ATG5) with asthma." (PMID 34019141, 2021).
asthma (continued). "Early studies discovered genetic polymorphisms of the ATG5 and ATG7 genes in individuals with pediatric and adult asthma that were linked to airway remodeling and impairment in respiratory system mechanics." (PMID 34204710, 2021). "Bronchial biopsy tissues from 42 asthmatics (15 mild, 12 moderate, and 15 severe) and 15 non-asthmatic healthy subjects were used to measure and assess correlation between ATG5 protein expression and asthma per se and severity." (PMID 28424691, 2017). "Further, we demonstrated that Atg5 mRNA expression is up-regulated in human nasal epithelial cells during an acute asthma attack." (PMID 22536318, 2012). "By screening the autophagy genes ATG5 and ATG7, we found evidence of association with variants in ATG5 with childhood asthma." (PMID 22536318, 2012). "Associations between two genes in the autophagy pathway, ATG5 and ATG7, with childhood asthma were investigated." (PMID 22536318, 2012). "Previous studies of autophagy genes and asthma have shown an association with variants in ATG5, but a comprehensive analysis of autophagy related genes and asthma has not been performed." (PMID 41929293, 2026). "In respiratory epithelial cells of patients with severe asthma, the expression level of Atg5 protein is increased, and this phenomenon is closely related to the deepening of the degree of fibrosis in the lower cell layer as well as the increase of collagen-1 expression." (PMID 39544928, 2024). "Additionally, ATG5 is a key protein involved in the formation of autophagosomes overexpressed in lung tissue of asthma patients." (PMID 38666016, 2024). "Autophagy-related 5 (ATG5) has attracted wide attentions in asthma." (PMID 37919667, 2023). "Notably, ATG5 was elevated in asthma patients at exacerbation compared to those at remission [median (interquartile range): 53.6 (37.6–90.0) vs. 35.6 (28.2–51.5) ng/mL] (P < 0.001)." (PMID 37644509, 2023). "Our study revealed that in adult asthma patients, ATG5 was positively related to the Th2/Th1 ratio." (PMID 37644509, 2023). "Still, despite some data indicate a link between atg5 polymorphisms and asthma severity, subsequent studies did not detect an association of Atg5 gene polymorphisms with asthma severity, suggesting the need to further clarify this pathological association." (PMID 37627282, 2023). "In conclusion, serum ATG5 is positively correlated with the Th2/Th1 ratio, proinflammatory cytokines, and exacerbation in adult asthma patients, which may have important clinical significance for the management of asthma." (PMID 37644509, 2023). "Previous reports suggest that compared with HCs, ATG5 is highly expressed in asthma children." (PMID 37644509, 2023). "However, increased ATG5 was correlated with male (P = 0.022) and a family history of asthma (P = 0.035)." (PMID 37644509, 2023). "Therefore, the relationship between ATG5 and inflammatory cytokines in adult asthma patients is worth focusing on." (PMID 37644509, 2023). "MiR-335-5p and miR-30a target ATG5 to suppress asthma inflammation." (PMID 37090692, 2023). "In terms of inflammatory cytokines, ATG5 was positively associated with TNF-α (rs=0.247, P < 0.001), IL-1β (rs=0.233, P = 0.001), IL-6 (rs=0.213, P = 0.003), and IL-17 (rs=0.154, P = 0.029) in adult asthma patients." (PMID 37644509, 2023). "Moreover, one study suggests that suppressing ATG5 inhibits autophagy in bronchial epithelial cells, which reduces airway fibrosis and airway remodeling, thus alleviating asthma." (PMID 37644509, 2023). "Interestingly, ATG5 was gradually reduced from M0 to M3 in adult asthma patients after treatment (P < 0.001)." (PMID 37644509, 2023). "In addition, ATG5 disclosed a good value to distinguish adult asthma patients from HCs with area under curve (AUC) of 0.829 (95% confidence interval (CI): 0.779–0.879)." (PMID 37644509, 2023). "Similarly, Atg5 is correlated with reduced lung function and airway remodeling in patients with severe asthma." (PMID 37627282, 2023).